RBM45 (RNA binding motif protein 45)
Description:
RNA-binding protein with binding specificity for poly(C). May play an important role in neural development.
Synonyms: RB-1; DRB1; FLJ44612
Tractability: PROTAC: UniProt records ubiquitination sites on it; ubiquitination databases record sites on it; its protein half-life has been measured.
Gene: Protein-coding gene on chromosome 2 (178,112,385 to 178,139,011, forward strand). Ensembl gene ENSG00000155636.
Subcellular location: Cytoplasm; Nucleus
Subcellular location (Human Protein Atlas): Nucleoplasm
Gene Ontology:
Molecular function: protein binding; RNA binding; nucleic acid binding
Biological process: nervous system development
Cellular component: cytoplasm; nucleoplasm; nucleus; ribonucleoprotein complex
Genetic constraint (gnomAD): Loss-of-function variants: 30 observed, 45.32 expected, observed/expected ratio (o/e) 0.66, 90% interval 0.49 to 0.9. The upper end of that interval is the gene's LOEUF score, 0.9, which puts it in group 3 of 6, group 1 being the genes least tolerant of losing a copy. Missense variants: 405 observed, 519.51 expected, observed/expected ratio (o/e) 0.78, 90% interval 0.72 to 0.85. Synonymous variants: 163 observed, 184.55 expected, observed/expected ratio (o/e) 0.88, 90% interval 0.78 to 1.01.
Homologues: Orthologues: chimpanzee RBM45 (100% identical), macaque RBM45 (99% identical), rabbit RBM45 (98% identical), dog RBM45 (98% identical), pig RBM45 (97% identical), guinea pig RBM45 (95% identical), rat Rbm45 (92% identical), mouse Rbm45 (91% identical), tropical clawed frog rbm45 (67% identical), zebrafish rbm45 (61% identical), Drosophila melanogaster CG1316 (37% identical). Paralogues in human: PABPC1 (18% identical), PABPC3 (18% identical), PABPC4 (18% identical), TARDBP (16% identical), PABPC1L (16% identical), ELAVL4 (14% identical), PUF60 (14% identical), SYNCRIP (14% identical), ELAVL2 (13% identical), ELAVL3 (13% identical), HNRNPR (13% identical), ELAVL1 (12% identical), and 12 more.
Diseases named in the same sentence as RBM45 in open-access papers:
RBM45 is named in the same sentence as 17 diseases in open-access papers, as found by Europe PMC text mining. Sharing a sentence is not in itself a finding about the gene and the disease. The quoted sentences say what the papers report.
amyotrophic lateral sclerosis (6 papers, 2012 to 2024). Amyotrophic lateral sclerosis (ALS) is a neurodegenerative disease characterized by progressive muscular paralysis reflecting degeneration of motor neurons in the primary motor cortex, corticospinal tracts, brainstem and spinal cord. "Mutations in RBM45 have been found linked to amyotrophic lateral sclerosis (ALS) and frontotemporal lobar dementia (FTLD)." (PMID 39122006, 2024). "The RNA binding protein (RBP) RBM45 forms nuclear and cytoplasmic inclusions in neurons and glia in amyotrophic lateral sclerosis (ALS), frontotemporal lobar degeneration with TDP-43 proteinopathy (FTLD-TDP), and Alzheimer’s disease (AD)." (PMID 32586379, 2020). "For instance, mutant R521C stabilizes FUS in amyotrophic lateral sclerosis (ALS) patients, facilitating its interaction with RBM45, and decreases the recruitment of HDAC1 to contribute to the pathogenesis of ALS16." (PMID 35654793, 2022). "The RBM45 (RNA-Binding Motif 45) protein translocates from nuclear to accumulate into the cytosol in Amyotrophic Lateral Sclerosis (ALS) patients." (PMID 31903115, 2020). "RBM45 is a developmentally regulated RNA binding protein (RBP) that forms nuclear and cytoplasmic inclusions in neurons and glia in amyotrophic lateral sclerosis (ALS), frontotemporal lobar degeneration with TDP-43 proteinopathy (FTLD-TDP), and Alzheimer’s disease (AD)." (PMID 32586379, 2020).
Alzheimer disease (4 papers, 2012 to 2023). A progressive, neurodegenerative disease characterized by loss of function and death of nerve cells in several areas of the brain leading to loss of cognitive function such as memory and language. "We also detected RBM45 cytoplasmic inclusions in 91 % of ALS, 100 % of FTLD-TDP and 75 % of Alzheimer’s disease (AD) cases." (PMID 22993125, 2012). "Control subjects, including both non-neurologic controls and Alzheimer’s disease, exhibited a punctate or speckled RBM45 pattern within the nucleus of dentate granule cells." (PMID 22993125, 2012).
hepatocellular carcinoma (2 papers, 2024 to 2025). A malignant tumor that arises from hepatocytes. "RBM45 downregulation suppresses hepatocellular carcinoma proliferation, while SRSF9 stabilizes oncogenic transcripts like DSN1, which correlates with lymph node metastasis and an advanced stage of CRC." (PMID 40724932, 2025). "For instance, phosphorylation mediated by RNA-binding motif protein 45 (RBM45) enhances alanine-serine-cysteine transporter 2 (ASCT2) stability and expression in hepatocellular carcinoma." (PMID 38439082, 2024).
autoimmune disease (1 paper, 2020). A disorder resulting from loss of function or tissue destruction of an organ or multiple organs, arising from humoral or cellular immune responses of the individual to their own tissue constituents. "The association of RNA-binding motif protein 45 (RBM45) with ITP or other autoimmune diseases is unknown." (PMID 32258092, 2020).
Azoospermia (1 paper, 2023). Absence of any measurable level of sperm,whereby spermatozoa cannot be observed even after centrifugation of the semen pellet. "We randomly chose five structures of other nucleic acid-bound RRM1 motifs, including human RBM45 (PDB ID: 7CSZ), DAZL (azoospermia (DAZ)-like) (PDB ID: 2XS5), hnRNP A1 (PDB ID: 5MPG), U2AF2 (PDB ID: 6XLW), and IMP3 (PDB ID: 6GX6), for comparison." (PMID 37253421, 2023).
lung adenocarcinoma (1 paper, 2025). A carcinoma that arises from the lung and is characterized by the presence of malignant glandular epithelial cells. "We revealed the collaborative mechanism between circ0515 and RBM45 in lung adenocarcinoma and further clarified their role in promoting cisplatin resistance." (PMID 40617805, 2025).
lung carcinoma (1 paper, 2025). "Interestingly, receiver operating characteristic (ROC) curve analysis demonstrated that RBM45 has potential diagnostic value for lung cancer." (PMID 40617805, 2025). "Further analysis revealed that SDHB is significantly upregulated in lung cancer and that RBM45 expression is significantly positively correlated with SDHB expression in lung cancer." (PMID 40617805, 2025). "The findings confirmed that RBM45 expression is markedly elevated in lung cancer tissues compared to control tissues." (PMID 40617805, 2025). "Inhibiting its expression significantly suppressed lung cancer cell proliferation, Analysis of The Cancer Genome Atlas (TCGA) database revealed that RBM45 is significantly upregulated in lung cancer." (PMID 40617805, 2025). "Based on these results, we propose that circ0515 and RBM45 collaboratively promote mitochondrial metabolism and energy generation, conferring greater survival and drug resistance to lung cancer cells." (PMID 40617805, 2025). "Notably, lung cancer patients with high RBM45 expression exhibited significantly shorter overall survival compared to those with low expression." (PMID 40617805, 2025). "Cell proliferation assays showed that the inhibitory effects of circ0515 knockdown on lung cancer cell proliferation could be rescued by overexpression of RBM45 and SDHB, respectively." (PMID 40617805, 2025). "Moreover, we found that activation of the circ0515/RBM45/SDHB axis increases cisplatin resistance in lung cancer cells, potentially by enhancing oxidative phosphorylation, reducing cisplatin-induced ROS damage, and inhibiting apoptosis." (PMID 40617805, 2025). "To further clarify the target genes co-regulated by circ0515 and RBM45, we performed RNA sequencing on A549 lung cancer cells with knockdown of circ0515 and RBM45, identifying 680 and 327 significantly downregulated differential target genes (LogFC < 1, p < 0.001), respectively." (PMID 40617805, 2025). "Similarly, the inhibitory effects of RBM45 knockdown on lung cancer cell proliferation could be rescued by overexpression of circ0515." (PMID 40617805, 2025). "Finally, whether the circ0515/RBM45/SDHB signaling axis functions broadly across various cancers or represents a lung cancer-specific mechanism remains unresolved." (PMID 40617805, 2025). "On the other hand, circ0515 recruited RNA binding motif protein 45 (RBM45) to stabilize SDHB mRNA, promoting SDHB expression and mitochondrial oxidative phosphorylation and succinate metabolism, leading to increased cisplatin resistance in lung cancer cells." (PMID 40617805, 2025). "Although the function of RBM45 in lung cancer has not been reported, our qPCR and Western blot experiments revealed that RBM45 expression is significantly upregulated in lung cancer cell lines." (PMID 40617805, 2025). "On the other hand, circ0515 synergizes with RBM45 to maintain the stability of the SDHB transcript, increase SDHB protein expression, promote mitochondrial oxidative phosphorylation and succinate metabolism, and ultimately enhance cisplatin resistance in lung cancer cells." (PMID 40617805, 2025).
neuroblastoma (1 paper, 2015). Neuroblastoma (NB) is the most common solid, extracranial childhood tumor. "Our results showed that endogenous RBM45 in human SHSY5Y and mouse Neuro2A neuroblastoma cells are located predominantly in the nucleus." (PMID 26391765, 2015).
nonalcoholic fatty liver disease (1 paper, 2023). "Previous studies have reported the regulation of splicing machinery by RBM45 in liver biopsies from patients with nonalcoholic fatty liver disease." (PMID 37547318, 2023).
neurologic disease (5 papers, 2012 to 2023). "Aberrant expression, dysfunction and particularly the aggregation of a group of RNA-binding proteins, including TDP-43, FUS and RBM45, are associated with several neurological disorders." (PMID 37296572, 2023). "Aberrant expression, dysfunction and particularly aggregation of a group of RNA-binding proteins, including TDP-43, FUS and RBM45, are associated with neurological disorders." (PMID 30992467, 2019). "Glial cells in ALS patients contained significantly more RBM45 nuclear inclusions per cell than those from non-neurologic disease controls (p < 1 × 10− 8)." (PMID 32586379, 2020). "In motor neurons from non-neurologic disease control subjects, RBM45 immunoreactivity was largely nucleolar (arrowheads) and SAFB and TDP-43 immunoreactivity was diffuse." (PMID 32586379, 2020). "FTLD-TDP subjects exhibited significantly more RBM45 inclusions than non-neurologic disease controls, AD, or ALS subjects (p < 1 × 10− 6 for control and AD and p < 0.01 for ALS versus FTLD-TDP, respectively)." (PMID 32586379, 2020). "In non-neurologic disease controls, RBM45 exhibited diffuse nuclear and strong perinucleolar immunoreactivity in dentate gyrus granule cells (arrowheads)." (PMID 32586379, 2020). "Non-neurologic disease control subjects exhibited a punctate staining pattern for RBM45 in the nucleus and cytoplasm of motor neurons in the lumbar spinal cord, with limited staining of nuclei within glial cells." (PMID 22993125, 2012). "We observed RBM45 nuclear inclusions in some aged non-neurologic disease controls, though this may be due to the normal aging process as seen with other RBPs." (PMID 32586379, 2020). "While genetic alterations of RBM45 have not yet been identified in neurologic diseases, the physical association of RBM45 with ALS-linked proteins suggests that it may play a role in regulating the normal function of these proteins in RNA metabolism." (PMID 26391765, 2015). "We also quantified RBM45 pathology in the lumbar spinal cord of ALS and non-neurologic disease controls." (PMID 32586379, 2020). "To better understand cell type- and disease-specific patterns of RBM45 inclusion pathology in neurodegenerative diseases, we performed an extensive quantification of RBM45 pathology in ALS, FTLD-TDP, AD, and non-neurologic disease controls." (PMID 32586379, 2020). "We first performed immunohistochemistry for RBM45, SAFB, and TDP-43 in the dentate gyrus of non-neurological disease controls, FTLD-TDP, ALS, and AD." (PMID 32586379, 2020). "Critically, this was not due to a general decrease in SAFB immunoreactivity, as neighboring cells without RBM45 nuclear inclusions showed strong SAFB immunoreactivity comparable to non-neurologic disease controls (inset)." (PMID 32586379, 2020). "Finally, we detected no RBM45 pathology in the hippocampus of any non-neurologic disease control case." (PMID 22993125, 2012). "RBM45 nuclear and cytoplasmic inclusions are found in both neurons and glia in ALS, FTLD-TDP, and AD but are absent in non-neurologic disease controls." (PMID 32586379, 2020). "RBM45 is frequently observed in cytoplasmic and nuclear inclusions in neurons and glia in FTLD-TDP, ALS, and AD, but not in non-neurologic disease controls." (PMID 32586379, 2020). "In the hippocampal dentate gyrus, numerous RBM45 nuclear inclusions with a punctate morphology were observed in FTLD, AD, and ALS subjects, but not in non-neurologic disease controls." (PMID 32586379, 2020).
cancer (4 papers, 2022 to 2025). A tumor composed of atypical neoplastic, often pleomorphic cells that invade other tissues. "CIAO1, CNOT2, and RBM45 were the candidate reference genes used in this study and were screened as stably expressed reference genes using pan-cancer transcriptome data." (PMID 37274277, 2023). "However, the functional mechanisms of RBM45 in cancer remain largely unexplored." (PMID 40617805, 2025).
neurodegenerative disease (4 papers, 2012 to 2024). A disorder of the central nervous system characterized by gradual and progressive loss of neural tissue and neurologic function. "RBM45 is an RNA binding protein involved in RNA processing and splicing and is associated with neurodegenerative disease and response to DNA damage." (PMID 36522653, 2022). "Abnormalities in RBM45 have been observed to be associated with certain neurodegenerative diseases." (PMID 39122006, 2024). "Mutation in one of these residues, Lys458, has been found linked to ALS and FTLD, suggesting that the RNA-binding ability/specificity of RBM45 is likely to play an important role in the development of these neurodegenerative diseases." (PMID 39122006, 2024). "Characterizing the RBM45-recognizing RNAs is essential for understanding the biological function of RBM45 as well as its aggregation in cells from patients with neurodegenerative diseases." (PMID 39122006, 2024). "Collectively, our results provide new insights into the biological functions of RBM45, the mechanisms by which RBM45 forms inclusions, and implicate NSBs in the pathogenesis of several neurodegenerative diseases." (PMID 32586379, 2020). "Across neurodegenerative diseases, RBM45 nuclear inclusion pathology occurs more frequently than cytoplasmic RBM45 inclusion pathology and exhibits cell type-specific variation." (PMID 32586379, 2020). "We established a connection between RBM45 and neurodegenerative disease by virtue of the cytoplasmic inclusion pathology observed in a total of 91 % of ALS, 100 % of FTLD-TDP and 75 % of AD cases." (PMID 22993125, 2012).
tumor (2 papers, 2022 to 2025). "This discovery reveals a novel molecular mechanism of circRNA and RBP in tumor metabolic regulation and provides theoretical support for developing circ0515 and RBM45 as potential therapeutic targets." (PMID 40617805, 2025).
hematological disorders (1 paper, 2020). "Thus, the identification of the RBM45 protein and its cognate binding site in B19V pre-mRNA provides a novel target for antiviral development to combat B19V infection-caused severe hematological disorders." (PMID 32156816, 2020).
RBM45 also shares sentences with these, for which no sentence is quoted: frontotemporal lobar degeneration (4 papers); glioblastoma (1); synucleinopathies (1).